GSTP1 (glutathione S-transferase pi 1)
Diseases named in the same sentence as GSTP1 in open-access papers (continued):
Sharing a sentence is not in itself a finding about the gene and the disease.
Thrombocytopenia (3 papers, 2018 to 2021). A reduction in the number of circulating thrombocytes. "A lower risk of thrombocytopenia was associated with the GSTP1 c.313A>G either dominant (AA vs. AG + GG; OR: 0.27, 95% CI: 0.12–0.64, P < 0.01) or recessive model (AA + AG vs. GG; OR: 0.18, 95% CI: 0.03–0.85, P = 0.03)." (PMID 33326171, 2021). "Patients with GSTP1 ile105val polymorphism had 2 (CI: 1.1-4.1) times higher risk for thrombocytopenia when compared to wild type." (PMID 31653159, 2019).
tuberculosis (3 papers, 2016 to 2025). A chronic, recurrent infection caused by the bacterium Mycobacterium tuberculosis. "Previous studies have reported associations between differential DNA methylation levels in promoter regions of genes encoding metabolic enzymes—such as CYP2E1, CYP2D6, GSTP1, and NAT2—and ATDILI risk in tuberculosis patients." (PMID 40133601, 2025). "Hypermethylation of GSTP1 may playroles in the development of anti-tuberculosis drug-induced liver injury." (PMID 30444463, 2018).
amyotrophic lateral sclerosis (2 papers, 2019 to 2021). Amyotrophic lateral sclerosis (ALS) is a neurodegenerative disease characterized by progressive muscular paralysis reflecting degeneration of motor neurons in the primary motor cortex, corticospinal tracts, brainstem and spinal cord. "Furthermore, GSTP1 polymorphisms and GSTP1-1 variants are involved in amyotrophic lateral sclerosis (ALS)." (PMID 31357662, 2019).
asbestosis (2 papers, 2013 to 2025). A lung disorder caused by inhalation of asbestos fibers. "Polymorphisms in glutathione S-transferase (GST) genes such as GSTM1 null, GSTT1 deletion, and high-activity GSTP1 genotypes have been associated with increased asbestosis risk, suggesting complex interactions in detoxification pathways." (PMID 41012395, 2025). "The study comprised 262 cases with asbestosis and 265 controls with no asbestos-related disease previously studied for MnSOD, ECSOD, CAT, GSTT1, GSTM1, GSTP1, and iNOS polymorphisms." (PMID 23984360, 2013).
atrophic gastritis (2 papers, 2012 to 2017). "The wild-type GSTP1 Ile/Ile genotype versus the variant genotypes Ile/Val + Val/Val was significantly associated with a decreased risk of gastric atrophy/intestinal metaplasia (OR = 0.60, 95% CI: 0.37–0.98)." (PMID 28182092, 2017). "Interaction between GSTP1 Ile/Val polymorphism and H. pylori infection, smoking, and alcohol consumption in atrophic gastritis." (PMID 23077566, 2012). "Despite the similar frequency of gastric atrophy in patients with variant GSTP1 Ile105Val genotype in Chinese and Romanian populations (37% versus 35.7%), environmental factors did not influence the role of this gene polymorphism in premalignant gastric lesions in our study." (PMID 28182092, 2017). "Compared with the wild-type Ile/Ile genotype, the variant Ile/Val + Val/Val genotypes of GSTP1 Ile105Val gene polymorphism were significantly associated with a decreased risk of gastric atrophy/intestinal metaplasia (adjusted OR = 0.60, 95% CI: [0.37, 0.98]) after adjusting for age and sex." (PMID 28182092, 2017).
bladder tumors (2 papers, 2013 to 2014). "For example, the high content of GSTP1 in urothelium may be responsible for the detoxification of benzo[a]pyrene dihydrodiol epoxide, but at the same time, overexpression of GSTP1, very often observed in urinary bladder tumors, may be linked with drug resistance during chemotherapy." (PMID 24919441, 2014). "Several studies have shown that glutathione S-transferase P1 (GSTP1), GSTM1 and GSTT1 are highly expressed in urinary bladder tissues and showed significantly higher activity and expression of these enzymes in bladder tumors than in normal uroepithelium." (PMID 24919441, 2014). "As methylation reduces gene expression, our data are in agreement with those of Pljesa-Ercegovac, the absence of GSTP1 methylation observed in our study supporting the hypothesis of more aggressive behavior of bladder tumors and consequently of a higher relapse rate." (PMID 24252461, 2013).
chronic lymphocytic leukemia (2 papers, 2019 to 2024). "Yuille and co-workers studied the relationship between genotypes of GSTM1, GSTT1, GSTP1, and chronic lymphocytic leukemia (CLL)." (PMID 31681592, 2019).
cleft lip (2 papers, 2021 to 2023). Congenital defect in the upper lip where the maxillary prominence fails to merge with the merged medial nasal prominences. "In humans, a functional polymorphism of GSTP1 is associated with non-syndromic cleft lip risk, with risk modified in the presence of maternal smoking." (PMID 34943067, 2021).
colitis (2 papers, 2020 to 2024). Inflammation of the colon. "We found that colitis significantly decreased GST classes alpha, mu, and pi (GSTA3, GSTM1, GSTP1)." (PMID 38668322, 2024).
colorectal tumor (2 papers, 2015 to 2021). "We have recently shown that thiazolides, a novel class of anti-infectious drugs, induce apoptosis in colorectal tumor cells in a GSTP1-1-dependent manner, thereby bypassing this GSTP1-1-mediated drug resistance." (PMID 26043078, 2015). "Specifically, GST of the class P1 (GSTP1-1) is overexpressed in colorectal tumor cells and renders them resistant to various drugs." (PMID 26043078, 2015). "Yet, the combination of restricted GSTP1-1 expression and proliferation status may protect tissue cells and bone marrow cells from thiazolide-induced destruction, while it renders tumor cells, specifically colorectal tumor cells, highly sensitive to thiazolide-induced apoptosis." (PMID 26043078, 2015).
diffuse large B-cell lymphoma (2 papers, 2014 to 2019). "Finally, frequency of GSTP1 aberrant methylation in diffuse large B-cell lymphoma (DLBCL) also led to studies to validate the prognostic impact of such epigenetic alteration in these lymphomas." (PMID 25076909, 2014).
end-stage renal disease (2 papers, 2020 to 2024). "Neither were the GST polymorphisms associated with any microvascular complications among Slovenian T2DM patients, while GSTP1 rs1138272 showed a nominal association with the risk for end-stage renal failure due to DKD." (PMID 38539811, 2024). "Furthermore, in T2DM patients without end-stage renal failure, GSTP1 rs1695 and predicted GSTP1 activity were nominally associated with the development and severity of albuminuria." (PMID 38539811, 2024).
endometriosis (2 papers, 2015 to 2016). The growth of functional endometrial tissue in anatomic sites outside the uterine body. "To compare our findings, we search the PubMed database for studies that examined the association between GSTM1, GSTT1, and GSTP1 313 A/G polymorphisms with endometriosis up to July 2014." (PMID 27351025, 2016). "Accordingly, we investigated the association between GSTM1, GSTT1 and GSTP1 variations and susceptibility to endometriosis in Iranian women." (PMID 27351025, 2016). "Only one out of five studies, in a Turkish population, reported that there is a positive association between GSTP1 313 A/G and endometriosis." (PMID 27351025, 2016). "We examined the associations of GSTM1 and GSTT1 null genotypes and GSTP1 313 A/G polymorphisms with endometriosis in an Iranian population." (PMID 27351025, 2016). "Also, GSTP1 313 A/G polymorphism was associated with the endometriosis, however, 313 A/G genotype had a protective effect (p=0.048, OR=0.61), which decreases the risk of the disease." (PMID 27351025, 2016). "The aim of this study was to evaluate whether the GSTM1, GSTT1 null genotypes and GSTP1 313 A/G polymorphism are associated with susceptibility to endometriosis." (PMID 27351025, 2016). "Our results showed that GSTM1 and GSTP1 polymorphisms may be associated with susceptibility of endometriosis in Iranian women." (PMID 27351025, 2016). "Summary of studies which evaluated the GSTM1, GSTT1 and GSTP1 variations in endometriosis." (PMID 27351025, 2016). "Inactivating gene mutations, polymorphisms, and allelic variants of the detoxification genes, including cytochrome P450 family (CYP1A1 and CYP2D6) and GST family (GSTT1, GSTP1, and GSTM1), which are associated with impaired functions, may be implicated in endometriosis susceptibility." (PMID 26185594, 2015). "Several studies demonstrated, however, that expression of antioxidant genes, NQO1, GSTP1, and GPX, was decreased in endometriosis, suggesting downregulation of oxidative metabolism genes." (PMID 26185594, 2015). "According to our knowledge, the results of GSTP1 313 A/G polymorphism and GSTM1 null deletions with the endometriosis are not consistent." (PMID 27351025, 2016).
epilepsy (2 papers, 2019 to 2021). A brain disorder characterized by episodes of abnormally increased neuronal discharge resulting in transient episodes of sensory or motor neurological dysfunction, or psychic dysfunction. "High levels of GSTP1-1 expression have been observed in endothelial and astrocytic cells in cases of intractable epilepsy, which would seem to be associated with resistance to antiepileptic drug treatment." (PMID 31357662, 2019). "An evidence for the resistance to antiepilectic drugs derived from a correlation between increased level of GSTP1-1 in the brain and medical intractability of epilepsy." (PMID 31357662, 2019).
Erythema (2 papers, 2011 to 2012). Redness of the skin, caused by hyperemia of the capillaries in the lower layers of the skin. "Further, the association of erythema with the presence of a mut/het of XRCC1 Arg194Trp or mut/het of GSTP1 was also found to be statistically significant indicating the protective role of these polymorphisms." (PMID 21749698, 2011). "Our results show a level that is not statistically significant in the protection towards developing an erythema, i.e. lower odds (OR = 0.3; 95% CI, 0.08-1.08), in the presence of at least one allelic variant (mut/het i.e. aa/Aa) of XRCC1 Arg194Trp or of GSTP1 (Ile105Val)." (PMID 21749698, 2011).
esophageal squamous cell carcinoma (2 papers, 2019 to 2020). Esophageal squamous cell carcinoma (ESCC) is a type of esophageal carcinoma (EC) that can affect any part of the esophagus, but is usually located in the upper or middle third. "In addition, the effect of GSTP1 on cell proliferation and apoptosis has been examined in esophageal squamous cell carcinoma cell lines." (PMID 33087132, 2020). "In a recent study, there was a significant association between GSTP1 expression in resected tissue and biopsy samples in patients with esophageal squamous cell carcinoma without neoadjuvant chemotherapy." (PMID 31357662, 2019). "GSTP1 was related to malignant potential and may be a predictive marker of drug resistance in esophageal squamous cell carcinoma patients." (PMID 31357662, 2019).
fatty liver disease (2 papers, 2013 to 2016). A reversible condition wherein large vacuoles of triglyceride fat accumulate in liver cells via the process of steatosis. "Amongst the top Toxicity functions was hepatic steatosis (p = 6.99x10-4) with associated genes including Acaca, Cbs, Ccnd1, Cyp4a11, Ddc, Gstp1, Insig2, Por and Rorc." (PMID 26968002, 2016).
fibrosis (2 papers, 2012 to 2023). the formation of excess fibrous connective tissue in an organ or tissue in a reparative or reactive process. "In particular, we found that the polymorphic variant (aa, Aa) of GSTP1 (Ile105Val), producing a protein with reduced activity, is associated with higher risk of developing (G2 or more) a fibrosis or fat necrosis." (PMID 22272830, 2012).
fluorosis (2 papers, 2015 to 2022). "It was observed that the activity of GST pi class (GSTP1), encoded by GSTP1 gene, directly related with the clinical feature of fluorosis." (PMID 26046522, 2015). "Therefore, we investigated the association between GSTP1 Rs1695 SNP and the susceptibility to brick-tea type of fluorosis." (PMID 26046522, 2015). "The activity of GSTP1, a phase II metabolizing enzyme, directly related with the clinical feature of fluorosis." (PMID 26046522, 2015). "Therefore, the reduced risks of brick-tea type of fluorosis associated with G allele of GSTP1 Rs1695 are consistent with the evidence indicating that the activity of GSTP1 directly related with the clinical feature of fluorosis." (PMID 26046522, 2015).
gastritis (2 papers, 2021 to 2025). Inflammation of the stomach. "As shown, carriers of the H3 haplotype, comprising GSTP1*G and GSTP1*T variant alleles, presented a more than 3-fold higher risk of HP-positive gastritis development (OR = 3.12, 95%CI = 1.29–7.67, p = 0.012), while the GSTO haplotype did not exert significant influence." (PMID 39859205, 2025). "The increased abundance of GSTP1-1 in AAG may be a mechanism to counteract oxidative stress, which is known to occur in stomach disorders, including gastritis." (PMID 33620602, 2021).
granulocytopenia (2 papers, 2020 to 2023). "When GSTP1 enzymatic activity is impaired, as is the case with the rs1695 missense variant, platinum‐based chemotherapy‐induced granulocytopenia was shown to be more common in a meta‐analysis of 12 case control trials." (PMID 35906899, 2023).
Hepatitis (2 papers, 2012 to 2025). Inflammation of the liver. "In this study, we observed that only the 5′ region of the 32 CpG sites examined (numbered −28 to +4 relative to the transcription start site) in the promoter region of the GSTP1 gene that are methylated specifically in HCC compared to normal liver and hepatitis and cirrhotic liver tissues." (PMID 22536438, 2012).
hepatoblastoma (2 papers, 2021 to 2024). Hepatoblastoma (HB) is a malignant hepatic tumor and is the most common pediatric liver cancer. "HepG2 is a hepatoblastoma cell line with relatively low GSTP1 protein expression, indicating that PCSK9 may affect the growth of HepG2 cells through other mechanisms, a possibility to be addressed in our future research." (PMID 33893729, 2021).
infertile (2 papers, 2018 to 2023). "Next, we investigated whether the selected candidates, GSTP1, GSTO2, and GSTK1, played important roles in the observed infertility caused by decreased Klotho expression." (PMID 37759974, 2023). "In addition, GSTP1 wild-type genotype in combination with GSTM1 null or GSTT1 null genotype increased the probability for infertility." (PMID 29766145, 2018). "After analysis of the published dataset (GSE6872,), the mRNA levels of GSTP1, GSTO2, and GSTK1 were remarkably reduced in sperm from infertile men, who had severe sperm morphological defects, compared to sperm from fertile individuals." (PMID 37759974, 2023).
injury (2 papers, 2018 to 2020). Damage inflicted on the body as the direct or indirect result of an external force, with or without disruption of structural continuity. "This is notable because GSTP1 and PARK-7 play an important antioxidant role following brain injury." (PMID 30274397, 2018).
insomnia (2 papers, 2024 to 2025). A sleep disorder characterized by difficulty in falling asleep and/or remaining asleep. "Notably, apart from three proteins [one protein instrumented in each tissue (FCG2A and FCG2B) and one instrumented in both (GSTP1)], all the proteins associated with insomnia also had concordant associations with leisure screen time." (PMID 38397929, 2024). "Moreover, the GSTP1 (p = 0.034) and Parvimonas micra (p = 0.046) levels in the insomnia group were numerically lower than in the subclinical insomnia group." (PMID 41562844, 2025). "S. aureus is related to GSTP1 content in the insomnia group as well." (PMID 41562844, 2025).
kidney cancer (2 papers, 2013 to 2016). Primary or metastatic malignant neoplasm involving the kidney. "In addition, GSTP1 expression is highly correlated with carcinogenesis; GSTP1 is overexpressed in a variety of human cancers, including lung, colon, ovary, bladder and kidney cancer." (PMID 23426146, 2013).
lung squamous cell carcinoma (2 papers, 2013 to 2014). "GSTP1, HSPB1 and CKB were found to be novel potential biomarkers for early detection of lung squamous cell carcinoma by using iTRAQ-tagging combined with two-dimensional liquid chromatography tandem MS analysis, while GSTP1 down-regulation is involved in human bronchial epithelial carcinogenesis." (PMID 23339750, 2013).
migraine (2 papers, 2022 to 2025). "Haplotype association analysis of the GSTP1 rs1138272 and rs1695 variants with alcohol as migraine trigger." (PMID 36698892, 2022). "Nevertheless, a significant association of alcohol consumption reported as migraine trigger with the presence of the variant allele haplotype of GSTP1 rs1695 and rs1138272 [Val105/Val114 or Grs1695T rs1138272 (GSTP1*C) haplotype] was revealed in the migraine cohort of the current study." (PMID 36698892, 2022). "They demonstrated statistically significant associations of selected variants for the haplotype of glutathione S-transferase Pi 1 (GSTP1), which affects brain cell detoxification, with alcohol consumption as a trigger for migraine attacks." (PMID 41305669, 2025). "Lastly, variability in the CAT, GSTP1 and UCP2 genes were associated with sleep/weather changes, alcohol consumption and physical exercise, respectively, as migraine triggers." (PMID 36698892, 2022). "The current study did not detect any significant association of the GSTP1 variants with the susceptibility to develop migraine or migraine subtypes and clinical phenotypes." (PMID 36698892, 2022).
Motor Neuron Disease (2 papers, 2021 to 2025). "The presence of the CT variant at codon 114 of GSTP1 is linked to an increased susceptibility to motor neuron disease while GSTP1 polymorphisms are observed to be prevalent in progressive bulbar palsy." (PMID 40290119, 2025). "Despite these descriptions, there is only one study describing the role of the GSTP1 rs1695 polymorphism in ALS, two studies with patients with Motor Neuron Disease (MND), and there are no published data for a study conducted in Brazil." (PMID 33606765, 2021).
multiple myeloma (2 papers, 2019 to 2020). "GSTP1 105 variant of this enzyme has less ability for detoxification, therefore the effectivity of cytostatic agents is increased in such multiple myeloma patients." (PMID 31506802, 2020).
Myalgia (2 papers, 2022 to 2025). "Indeed, the data obtained showed that individuals carrying GSTP1 Val or GSTO1 Asp allele exhibit lower odds of long-COVID myalgia development, which was even more potentiated in individuals carrying both of these alleles." (PMID 35624818, 2022). "Indeed, individuals carrying GSTP1 Val or GSTO1 Asp allele exhibited lower odds of long-COVID myalgia development, both independently and in combination." (PMID 35624818, 2022). "The combined effect of risk genotypes (GSTP1 AB IleIle, GSTO1 AlaAla, GPX1 LeuLeu, and GPX3 CC) markedly increased the probability of myalgia, suggesting a cumulative genetic burden." (PMID 40867811, 2025). "On the other hand, the presence of GSTP1 Ile and GSTO1 Ala alleles exhibited cumulative risk regarding long-COVID myalgia in carriers of combined GPX1LeuLeu/GPX3CC genotype." (PMID 35624818, 2022). "In this study, apart from the GSTP1 Val allele, the GSTO1 Asp allele also exhibits a modifying effect on the probability of the occurrence of myalgia in long-COVID patients, which is even more potentiated in individuals carrying both of these alleles." (PMID 35624818, 2022). "Furthermore, the combined presence of GSTP1 Ile and GSTO1 Ala alleles exhibited cumulative risk regarding long-COVID myalgia in carriers of the combined GPX1 LeuLeu/GPX3 CC genotype." (PMID 35624818, 2022).